DAG1 (dystroglycan 1)
Description:
The dystroglycan complex is involved in a number of signaling events and processes including laminin deposition and extracellular matrix assembly, acetylcholine receptor clustering, sarcolemmal stability, cell survival, peripheral nerve myelination, nodal structure, cell migration, epithelial polarization, and epithelium branching morphogenesis (By similarity). Required for the formation of photoreceptor ribbon synapses, and long-term maintenance of inhibitory synapses in cerebellar Purkinje cells (By similarity). Also involved in the positive regulation of cartilage formation through agrin (AGRN) binding and up-regulation of SOX9, a transcription factor that plays a key role in chondrocytes differentiation. [Alpha-dystroglycan]: Extracellular peripheral glycoprotein that acts as a receptor for extracellular matrix proteins containing laminin-G domains. As a receptor for laminin is involved in extracellular matrix assembly, and activation of the PI3K/AKT pathway regulating cell apoptotic signals in muscle (By similarity). Binding of laminin LAMA1 to alpha-dystroglycan also initiates a signaling cascade in which Src kinases, c-Src or c-Fyn, phosphorylate syntrophin modifying its interaction with the adapter protein GRB2; this triggers recruitment of guanyl-nucleotide exchange factor SOS1 and activation of RAC1, finally resulting in c-Jun phosphorylation by MAPK8/JNK1 (By similarity). As a receptor for laminin LAMA1 is also involved in epithelium branching morphogenesis in salivary glang and lung (By similarity). Receptor for laminin-2 (LAMA2) and agrin in peripheral nerve Schwann cells (By similarity). Also acts as a receptor for laminin LAMA5 (By similarity). In muscle cells, it is a receptor for laminin-1 (also known as laminin-111 or EHS laminin) and is involved in the stimulation of agrin-induced acetylcholine receptor (AChR) clustering, and formation of the synaptic basement membrane. It is required for acetylcholinesterase (AChE) localization at the neuromuscular junctions (NMJ) through its binding with perlecan (HSPG2) and is, therefore, involved in the down-regulation of colinergic synaptic transmission (By similarity). In the retina, it is required for the formation of photoreceptor ribbon synapses through its interaction with pikachurin (EGFLAM) (By similarity). Involved in the positive regulation of cartilage formation through agrin (AGRN) binding and up-regulation of SOX9, a transcription factor that plays a key role in chondrocytes differentiation. [Beta-dystroglycan]: Transmembrane protein that plays important roles in connecting the extracellular matrix to the cytoskeleton. Acts as a cell adhesion receptor in both muscle and non-muscle tissues. Receptor for both DMD and UTRN and, through these interactions, scaffolds axin to the cytoskeleton. Also functions in cell adhesion-mediated signaling and implicated in cell polarity. [Alpha-dystroglycan]: (Microbial infection) Acts as a receptor for lassa virus and lymphocytic choriomeningitis virus glycoprotein and class C new-world arenaviruses. Acts as a Schwann cell receptor for Mycobacterium leprae, the causative organism of leprosy, but only in the presence of the G-domain of LAMA2.
Synonyms: A3a; 156DAG; AGRNR; DAG; LGMDR16; MDDGA9; MDDGC7; MDDGC9
Tractability: Small molecule: a structure with a bound ligand is known. Antibody: UniProt places it where antibodies can reach, with high confidence; its Gene Ontology location is reachable by antibodies, with high confidence; UniProt predicts a signal peptide or a membrane-spanning region; the Human Protein Atlas places it where antibodies can reach. PROTAC: ubiquitination databases record sites on it; its protein half-life has been measured.
Gene: Protein-coding gene on chromosome 3 (49,468,649 to 49,535,619, forward strand). Ensembl gene ENSG00000173402.
Subcellular location: Secreted, extracellular space (Alpha-dystroglycan); Secreted, extracellular space, extracellular matrix, basement membrane; Synapse; Cell membrane (Beta-dystroglycan); Cytoplasm, cytoskeleton; Nucleus, nucleoplasm; Cell membrane, sarcolemma; Postsynaptic cell membrane
Subcellular location (Human Protein Atlas): Plasma membrane; Vesicles; Nucleoplasm
Pathways (Reactome):
Metabolism of proteins: DAG1 core M1 glycosylations; DAG1 core M2 glycosylations; DAG1 core M3 glycosylations; Matriglycan biosynthesis on DAG1
Disease: Defective POMGNT1 causes MDDGA3, MDDGB3 and MDDGC3; Defective POMT1 causes MDDGA1, MDDGB1 and MDDGC1; Defective POMT2 causes MDDGA2, MDDGB2 and MDDGC2
Extracellular matrix organization: ECM proteoglycans; Formation of the dystrophin-glycoprotein complex (DGC); Non-integrin membrane-ECM interactions
Developmental Biology: EGR2 and SOX10-mediated initiation of Schwann cell myelination; Regulation of expression of SLITs and ROBOs
Gene Ontology:
Molecular function: actin binding; alpha-actinin binding; protein binding; serine-type endopeptidase activity; SH2 domain binding; structural constituent of muscle; tubulin binding; vinculin binding; virus receptor activity; laminin binding; laminin receptor activity; laminin-1 binding; calcium ion binding; dystroglycan binding; heparan sulfate proteoglycan binding; protein-containing complex binding
Biological process: basement membrane organization; membrane protein ectodomain proteolysis; microtubule anchoring; negative regulation of cell migration; negative regulation of MAPK cascade; negative regulation of phosphatidylinositol 3-kinase/protein kinase B signal transduction; axon guidance; extracellular matrix organization; inhibitory synapse assembly; morphogenesis of an epithelium; muscle attachment; nerve development; positive regulation of Rac protein signal transduction; angiogenesis involved in wound healing; axon regeneration; calcium-dependent cell-matrix adhesion; cellular response to cholesterol; cellular response to mechanical stimulus; extracellular matrix assembly; myelination in peripheral nervous system; nerve maturation; positive regulation of cell-matrix adhesion; positive regulation of myelination; positive regulation of oligodendrocyte differentiation; positive regulation of phosphatidylinositol 3-kinase/protein kinase B signal transduction; and 13 more
Cellular component: basement membrane; contractile ring; cytoplasm; dystrophin-associated glycoprotein complex; extracellular exosome; extracellular matrix; extracellular region; filopodium; focal adhesion; lamellipodium; membrane; nucleoplasm; plasma membrane; cytosol; dystroglycan complex; endoplasmic reticulum lumen; endoplasmic reticulum membrane; Golgi lumen; Golgi membrane; postsynaptic membrane; sarcolemma; synapse; adherens junction; basolateral plasma membrane; cell surface; and 14 more
Genetic constraint (gnomAD): Loss-of-function variants: 8 observed, 48.49 expected, observed/expected ratio (o/e) 0.16, 90% interval 0.096 to 0.3. The upper end of that interval is the gene's LOEUF score, 0.3, which puts it in group 1 of 6, group 1 being the genes least tolerant of losing a copy. Missense variants: 990 observed, 1,236.1 expected, observed/expected ratio (o/e) 0.8, 90% interval 0.76 to 0.84. Synonymous variants: 486 observed, 497.53 expected, observed/expected ratio (o/e) 0.98, 90% interval 0.91 to 1.05.
Gene-disease validity (ClinGen):
ClinGen rates the evidence that DAG1 causes each of these diseases.
neuromuscular disease caused by qualitative or quantitative defects of alpha-dystroglycan (autosomal recessive): Definitive.
Homologues: Orthologues: chimpanzee DAG1 (99% identical), macaque DAG1 (97% identical), pig DAG1 (95% identical), dog DAG1 (95% identical), rabbit DAG1 (94% identical), guinea pig DAG1 (93% identical), mouse Dag1 (93% identical), rat Dag1 (93% identical), tropical clawed frog dag1 (68% identical), zebrafish dag1 (60% identical), Drosophila melanogaster Dg (25% identical), Caenorhabditis elegans dgn-1 (17% identical), and 1 more.
Diseases named in the same sentence as DAG1 in open-access papers:
DAG1 is named in the same sentence as 71 diseases in open-access papers, as found by Europe PMC text mining. Sharing a sentence is not in itself a finding about the gene and the disease. The quoted sentences say what the papers report.
dystroglycanopathies (26 papers, 2012 to 2026). "Mutations in DAG1 or genes involved in the posttranslational processing of DG lead to a subset of neuromuscular diseases referred to as dystroglycanopathies." (PMID 42234522, 2026). "We analyzed different DG point-mutations linked to dystroglycanopathies, namely, L84F, T190M, I591D and C667F that were introduced in the coding sequence of murine dag1 cloned in a pEGFP-N1 vector." (PMID 40248434, 2025). "Variants in DAG1 have been associated with both type A and type C muscular dystrophy–dystroglycanopathy." (PMID 39897774, 2025). "Primary dystroglycanopathies are caused by homozygous mutations in the DAG1 gene, while secondary dystroglycanopathies are caused by mutations in genes involved in the alpha‐dystroglycan (αDG) glycosylation pathway." (PMID 38736632, 2024). "Mutations in Dag1 or the genes required for its glycosylation result in dystroglycanopathy, a type of congenital muscular dystrophy characterized by a wide range of phenotypes including muscle weakness, brain defects, and cognitive impairment." (PMID 38179984, 2024). "These genes encode various specific glycosyltransferases as well as enzymes preparing specific sugars to be incorporated into the matriglycan structure, and very few α-dystroglycanopathy cases involve mutations in the DAG1 gene itself." (PMID 32423971, 2020). "The novelty of our study is that it is a first report of DAG1 associated muscular dystrophy‐dystroglycanopathy (limb‐girdle), type C, 9 (MDDGC9) with mild and late age of onset." (PMID 30450679, 2019). "Mutations in DAG1 itself as well as 17 other genes have been reported in patients with dystroglycanopathy." (PMID 29855340, 2018). "Homozygous and compound heterozygous mutations in 17 genes, plus DAG1 itself, have been associated with dystroglycanopathies." (PMID 30060766, 2018). "Clinical conditions arising from mutations in DAG1 itself are referred to as primary α-dystroglycanopathies." (PMID 30578246, 2018). "Recently, a novel homozygous mutation in DAG1 has been identified in a Libyan family with two siblings affected by a dystroglycanopathy resembling a MEB-like condition." (PMID 26380289, 2015). "Similarly, fukutin mutation compromises the glycosylation of DAG1, leading to Fukuyama congenital muscular dystrophy, a milder dystroglycanopathy characterized by progressive muscle weakness and brain vessel dysfunction." (PMID 36463265, 2022). "For example, primary dystroglycanopathies result from a mutation in the Dg gene per se (DAG1 in vertebrates), while deficiencies in 17 genes encoding the enzymes involved in Dg glycosylation have been identified and associated with secondary dystroglycanopathies." (PMID 31959160, 2020). "However, DAG1 gene associated MDDGC9 is a very rare dystroglycanopathy and till now less than 10 cases reported worldwide." (PMID 30450679, 2019). "Interestingly, in the two zebrafish models of primary dystroglycanopathy, each caused by a different mutation in the dag1 gene, retracted fibers were reported to remain impermeable to EBD29 or to take up EBD only after retraction." (PMID 29188128, 2017). "In addition, mutations in laminin and DAG1 also cause dystroglycanopathies." (PMID 36463265, 2022). "Mice that model severe dystroglycanopathy due to forebrain deletion of Dag1 or Pomt2, which is required for Dystroglycan glycosylation, show significant impairment of CCK+/CB1R+ IN development." (PMID 38179984, 2024). "Dystroglycanopathies are a group of diseases characterized by impaired laminin-DAG1 interaction, including Walker-Warburg syndrome, muscle-eye-brain disease, and Fukuyama congenital muscular dystrophy." (PMID 36463265, 2022). "DAG1 is widely expressed in different human tissues, consistent with the multi-organ phenotypes of many individuals with the most severe forms of dystroglycanopathy." (PMID 29855340, 2018).
dystroglycanopathies (continued). "Emx1Cre:Dag1 cKO and Emx1Cre:Pomt2 cKO mice show Type II lissencephaly consistent with severe dystroglycanopathy, whereas B4gat1M155T/M155T and FkrpP448L/P448L mutants have relatively normal cortical development consistent with mild dystroglycanopathy." (PMID 38179984, 2024). "Knockout of Dag1 after synapse formation in adult animals likewise causes selective loss of CCK terminals, but there is no such phenotype in the Dag1 T190M knock-in mouse – a model of α-dystroglycanopathy expressing a neurexin-binding-deficient αDG." (PMID 30578246, 2018). "Patients with MDDGC9 usually identified with defective glycosylation of DAG1, hence it is known as “dystroglycanopathies”." (PMID 30450679, 2019). "In particular, it could be particularly interesting to focus on the 3′ region of DAG1, corresponding to the α/β-DG interface, the genetic clinical screenings carried out on still unassigned cases of myopathy presenting with symptoms that may suggest the presence of a dystroglycanopathy." (PMID 26380289, 2015). "However, the development and function of CCK+/CB1R+ INs has not been examined in mouse models that more broadly lack Dag1 throughout the CNS and thus more accurately reflect the neuropathology of dystroglycanopathy." (PMID 38179984, 2024).
muscular dystrophy (17 papers, 2007 to 2025). Muscular dystrophy (MD) refers to a group of more than 30 genetic diseases characterized by progressive weakness and degeneration of the skeletal muscles that control movement. "AC9 proximal proteins SNTA1 and dystroglycan (DAG1) regulate Nav1.5 currents and are linked to arrhythmia-prone long QT syndrome, Brugada’s syndrome, and muscular dystrophy, respectively." (PMID 40749829, 2025). "DAG1 related muscular dystrophy is very rare and till now only 10 mutations have been reported in DAG1 gene to be associated with muscular dystrophy." (PMID 30450679, 2019). "Mutations within the DG gene (DAG1) have been recently associated with two forms of muscular dystrophy, one displaying a milder and one a more severe phenotype." (PMID 26380289, 2015). "The third example relates to aberrations in three genes that separately cause different subtypes of muscular dystrophy: dystroglycan 1 (DAG1), dystrophin (DMD), and caveolin 3 (CAV3)." (PMID 24921629, 2014). "The “canonical” receptors, Dag1 and Itga7, are highly expressed and, when mutated, lead to congenital muscular dystrophies." (PMID 23109907, 2012). "As DG is involved in the development of basement membranes, it certainly is fundamental for normal human development, and the failure to identify null mutations in DAG1 linked to muscular dystrophies in humans is probably due to early embryonic lethality of such mutations." (PMID 26380289, 2015). "The major piece of data collected so far on the structure and function of DAG1 in zebrafish is the work published by Parsons and colleagues, which shows that the inactivation of the DG gene by antisense morpholino oligonucleotides causes severe muscular dystrophy in the adult stage." (PMID 17509131, 2007). "It has been shown that muscle fiber specific deletion of DAG1 leads to a mild form of muscular dystrophy." (PMID 36523505, 2022). "The DAG1 gene encodes dystroglycan protein (NP_004384), which is a dystrophin-associated glycoprotein (DAG) that is known to be responsible for muscular dystrophy (MD) and muscle-eye-brain disease." (PMID 35082294, 2022). "For example, DAG1 is a pivotal component of the dystrophin-glycoprotein complex and its dysfunction is related to many muscular dystrophies, amongst other diseases." (PMID 34046427, 2021). "However, some studies demonstrate that FKTN, POMT1, and DAG1 are involved in muscular dystrophy." (PMID 29949603, 2018). "The relationship between the common variants in LAMA2, DAG1 and ITGA7 that are associated with myopia and the mutations in these same genes causing muscular dystrophy is not clear." (PMID 36737489, 2023).
breast cancer (8 papers, 2003 to 2022). A primary or metastatic malignant neoplasm involving the breast. "DAG1 function in breast cancer has been suggested to be of paracrine nature through hAG/DAG-1 interaction and thus involved in tumor microenvironment organization." (PMID 36010848, 2022). "As expected, several of the genes associated with top differentially methylated probes between these groups have been previously implicated in breast cancer, including SDC2, PBK, ALOX12B, DAG1, ZNF382, and FST." (PMID 35564499, 2022). "A further four more proteins, namely, TGFβ1, DAG1, LGALSBP3, and LOXL2, were found to be common between DCIS and breast cancer (all grades)." (PMID 36010848, 2022). "Furthermore, the same research group showed that AGR2 and AGR3 were both co-expressed in estrogen receptor (EsR)-positive breast cancer and can physically interact with LY6/PLAUR Domain Containing 3 (LYPD3 /C4.4a) and extracellular alpha-dystroglycan (DAG-1)." (PMID 35965326, 2022).
Walker-Warburg syndrome (6 papers, 2019 to 2024). "Mutations in DAG1 have been found to contribute to Walker-Warburg syndrome and other muscular dystrophy-dystroglycanopathies which can be associated with HC." (PMID 38439105, 2024). "In addition, in a consanguineous Israeli-Arab family a homozygous loss-of-function mutation in the DAG1 gene was detected in infants with a congenital phenotype consistent with Walker–Warburg syndrome." (PMID 34976016, 2021). "The specificity of C20 antibody was demonstrated using both DG knockout C2C12 cells and primary fibroblasts from a subject with Walker–Warburg syndrome that do not express DAG1 gene all18." (PMID 30814495, 2019).
Primary dystroglycanopathy (5 papers, 2013 to 2023). "Primary dystroglycanopathies caused by mutations in the DAG1 gene encoding α- and βDG have been reported in two patients, affecting dystroglycan function by impairing glycosylation of αDG or by presumed disruption of the αDG – βDG binding interface." (PMID 24824861, 2014). "Primary dystroglycanopathy affecting the dystroglycan encoding gene (DAG1) itself is very rare and has only been described in one patient thus far." (PMID 23894383, 2013).
colorectal cancer (4 papers, 2021 to 2025). A primary or metastatic malignant neoplasm that affects the colon or rectum. "DAG1 encodes a cell adhesion molecule that is reported to be involved in the growth, invasion, and aggressive phenotype of various tumors, such as colorectal cancer, prostate cancer, and gastric cancer." (PMID 37014625, 2023). "AGRN and DAG1 have also been reported to be involved in ECM-receptor interactions in colorectal cancer." (PMID 40538442, 2025). "Other studies showed that reduced DAG1 protein expression is associated with poor outcome of colorectal cancer; downregulation of FN1 decreases proliferation, migration, and invasion of colorectal cancer cells, while TNC induces EMT and proliferation." (PMID 34938324, 2021).
viral infection (4 papers, 2011 to 2022). "In contrast, knockout of DAG1 in both A549 and 293T cells led to only moderate decreases in pseudotyped virus infection (23% to 38% reduction for A549; up to 63% reduction for 293T) across all LCMV strains." (PMID 35502904, 2022). "Thus, direct targeting of the key enzyme EXTL3 of the HS biosynthesis pathway proved the importance of HS as a host factor involved in viral infection of low affinity variants even in the presence of DAG1 and for high affinity variants in the absence of functional DAG1." (PMID 34648606, 2021). "In one case [293T ΔDAG1 infected with rVSV-ΔG(GFP)+WE54-GP], deletion of DAG1 had virtually no measurable impact on pseudotyped virus infection." (PMID 35502904, 2022).
cardiomyopathy (3 papers, 2021 to 2025). A disease of the heart muscle or myocardium proper. "However, the involvement of DAG1 in clusters *198, #2, #144, #112, #103, #118, #11, #89 and #63, appears to be related to cardiomyopathy, while it is more focused on ‘ECM proteoglycan components’ in cluster *211." (PMID 34046427, 2021).